SMPD1 (sphingomyelin phosphodiesterase 1)
Diseases named in the same sentence as SMPD1 in open-access papers (continued):
Sharing a sentence is not in itself a finding about the gene and the disease.
Farber disease (6 papers, 2019 to 2025). "Based on these findings, it is possible that Smpd1 inhibition improves the survival of psap−/− zebrafish by alleviating pathologies shared with the Gaucher and Farber disease models." (PMID 37183607, 2023). "In the context of the sphingolipid metabolic pathway, it is possible that SMPD1 knockout-induced ceramide depletion may counter ceramide accumulation in Farber disease and enhance lifespan in the Gaucher model by shifting complex sphingolipid catabolism toward ceramide instead of psychosine." (PMID 37183607, 2023).
Gaucher disease (6 papers, 2014 to 2025). Gaucher disease (GD) is a lysosomal storage disorder encompassing three main forms (types 1, 2 and 3), a fetal form and a variant with cardiac involvement (Gaucher disease - ophthalmoplegia - cardiovascular calcification or Gaucher-like disease). "Identified risk genes associated with Lewy body disease include GBA1, the causative gene for Gaucher disease; GALC, when deficient leading to Krabbe disease; and SMPD1, for which defects result in acid sphingomyelinase deficiency." (PMID 40577679, 2025). "Some examples are variants in the glucocerebrosidase (GBA), the sphingomyelin phosphodiesterase 1 (SMPD1), and the GTP cyclohydrolase 1 (GCH1) genes, responsible for Gaucher's disease, Niemann-Pick A disease, and dopa-responsive dystonia (DRD), respectively." (PMID 26942037, 2016). "At the same time, acid sphingomyelinase analysis carried out in all samples showed a normal activity except for three patients who had normal glucocerebrosidase enzyme activity, so they were not affected by Gaucher disease; in these patients, we found SMPD1 gene mutations responsible for ASMD." (PMID 38592326, 2024).
hepatocellular carcinoma (5 papers, 2013 to 2024). A malignant tumor that arises from hepatocytes. "Comparison of normal livers to hepatocellular carcinomas, using four independent sets of samples available in the Oncomine database, revealed significantly decreased levels of ASM (SMPD1) and S1P phosphatase (SGPP1) mRNA expression." (PMID 23724146, 2013).
ovarian carcinoma (5 papers, 2018 to 2021). A malignant neoplasm originating from the surface ovarian epithelium. "Survival analysis showed that the high levels of SPHK1, KDSR, SMPD1, GALC, SMPD2, UGCG and DEGS1 were associated with poor prognosis of OS in patients with ovarian cancer, among which DEGS1 was the most significant (P = 3E-04)." (PMID 34488809, 2021). "We observed that in breast and ovarian cancers, SMPD1 high patients had significantly better overall survival." (PMID 32221387, 2020). "Our results provide a rationale for testing the hypothesis that secretory SMPD1 could be used as a potential biomarker in ovarian cancer patients." (PMID 31049165, 2019). "In this exploratory study, we aimed to determine the tumor anatomy-attributed expression pattern of the top 3 candidate molecules – CD68, SMPD1, and LPAR3 – within complex ovarian cancer tissues." (PMID 31049165, 2019). "Herein, we focused and explored predominantly the observational findings highlighting similarities in expression patterns for CD68 and SMPD1 (also known as acid sphingomyelinase, ASMase, ASM) in macrophage/monocyte lineage cells within the ovarian cancer tissue." (PMID 31049165, 2019).
steatosis (5 papers, 2019 to 2025). Increased lipid within the cytoplasm of cells. "While inflammation and steatosis were the most prominent cardiac changes observed in tissue samples from Smpd1−/− mice, fibrosis was also evident." (PMID 40166006, 2025). "RBKS, but not SMPD1, was associated with metabolic and liver dysfunction markers, while SCARA5, TNFRSF12A, and SMOC2, but not GDF-8, were associated with insulin resistance markers, and steatosis grade in the OB group." (PMID 39407757, 2024).
colorectal cancer (4 papers, 2020 to 2025). A primary or metastatic malignant neoplasm that affects the colon or rectum. "The resistance to 5-FU in colorectal cancer has been linked with alterations in sphingomyelin (SM) and ceramide (Cer) levels, controlled by acid sphingomyelinase (SMPD1)." (PMID 39494346, 2024). "We found that 5-FU resistance in DLD-1/5-FU colorectal cancer cells was mainly associated with SM increase and Cer decrease, which are controlled by acid sphingomyelinase (SMPD1)." (PMID 32273521, 2020). "Furthermore, clinical colorectal cancer data set analysis showed that down-regulation of SMPD1 was associated with resistance to chemotherapy regimens that include 5-FU." (PMID 32273521, 2020). "SMPD1 could be treated as the critical prognostic biomarker in colorectal cancer." (PMID 32285560, 2020). "The genes in the reported colorectal cancer group include POLR1D, DGKB, SULT2B1 SMPD1 GOT2, MTHFD1L and ACADM." (PMID 32285560, 2020). "In this study, we conducted an analysis and screening of potential core pathways, specifically the Glycosphingolipid pathway, and identified four core genes (SMPD1, GLTP, B3GALT4, and ST8SIA6) in colorectal cancer based on data analysis from relevant databases." (PMID 39898245, 2025).
deficiencies (4 papers, 2013 to 2024). "NPB, also known as acid sphingomyelinase deficiencies (ASMDs), caused by mutations in the SMPD1 gene, is believed to result from affected cholesterol transfer by NPC2 protein and presents with enlarged liver and spleen or spleen alone in early childhood." (PMID 29227331, 2018). "More recently, a founder mutation in SMPD1, the gene for Niemann-Pick types A and B disease (acid sphingomyelinase deficiencies), was recognized as a novel susceptibility factor for PD in the Ashkenazi Jewish population." (PMID 24386122, 2013). "Niemann-Pick type A and B are defined as acid sphingomyelinase deficiencies (SMPD1 mutations)." (PMID 34086834, 2021).
Insulin resistance (4 papers, 2021 to 2024). Increased resistance towards insulin, that is, diminished effectiveness of insulin in reducing blood glucose levels. "MSR1, KYNU, and RBKS, but not SMPD1, were associated with metabolic and liver dysfunction markers, while SCARA5, TNFRSF12A, SMOC2, but not GDF-8, were associated with insulin resistance markers." (PMID 39407757, 2024).
schizophrenia (4 papers, 2022 to 2025). A major psychotic disorder characterized by abnormalities in the perception or expression of reality. "Our results showed a selective association of SMPD3 polymorphisms with a schizophrenia diagnosis and of SMPD1 expression in the PFC." (PMID 39825014, 2025). "An initial analysis of human gene polymorphisms and brain gene expression in schizophrenia patients identified an association of SMPD1 and SMPD3 genes coding for ASM and NSM." (PMID 39825014, 2025).
sphingolipidoses (4 papers, 2023 to 2025). "Finally, it is important to note that although SMPD1 loss leads to sphingolipidosis, elevated SMPD1 is also linked to multiple neurological and metabolic disorders." (PMID 37183607, 2023). "Continued mechanistic studies and examination of pharmacological Smpd1 inhibitors in the psap KO and other sphingolipidosis models could shed further light on the feasibility of this approach for targeted sphingolipidosis therapy." (PMID 37183607, 2023).
Cirrhosis (3 papers, 2022 to 2025). A chronic disorder of the liver in which liver tissue becomes scarred and is partially replaced by regenerative nodules and fibrotic tissue resulting in loss of liver function. "Patient 2, a 31-year-old woman with compound heterozygous SMPD1 mutations (c.[739G > A], c.[1801G > A]), had cirrhosis, dyslipidemia, and stable lung disease." (PMID 41211123, 2025). "The role of the SMPD1 gene c.132_143del, p.A46_L49del (c.108GCTGGC (p.38AL)) (rs3838786) variant in the development of cirrhosis remains to be studied." (PMID 36725747, 2023).
coronary artery disease (3 papers, 2022 to 2025). "Our findings of thickened coronary arteriolar walls align with previous studies showing coronary artery disease in NPD B 11, as well as increased inflammation and dedifferentiation of vascular smooth muscle cell from Smpd1−/− mice 31,33." (PMID 40166006, 2025).
dementia (3 papers, 2015 to 2024). Loss of intellectual abilities interfering with an individual's social and occupational functions. "Our findings included well-known dementia-associated protein biomarkers, such as BMP4, CD200, MANF, PLXNB1, PLXNB3, and SMPD1 for AD and BCAN, NCAN, and THY1 for VD, as well as uncovering novel proteins associated with AD or VD." (PMID 39226887, 2024). "Comparing the average of SHAP values for core proteins for all dementia subtypes, TNR showed the highest, followed by THY1 and SMPD1, and only these three proteins presented positive values due to the low proportion of AD and VD participants in the validation cohort." (PMID 39226887, 2024).
Hepatosplenomegaly (3 papers, 2014 to 2024). Simultaneous enlargement of the liver and spleen. "Since hepatosplenomegaly and splenomegaly are the most commonly observed clinical syndrome of NPB and higher incidence of neuronopathy with rapid progressive psychomotor deterioration are reported in NPA, we mainly focused on the expression patterns of SMPD1 in the brain, liver, and spleen." (PMID 36907956, 2023).
Hypercholesterolemia (3 papers, 2020 to 2022). An increased concentration of cholesterol in the blood. "Thus, our data suggest that EC-specific overexpression of the Smpd1 gene sensitizes the hypercholesterolemia-induced formation of ceramide-enriched MR clusters in the carotid arterial intima." (PMID 36252682, 2022). "Our results demonstrated that EC-specific overexpression of the Smpd1 gene enhanced hypercholesterolemia-induced neointimal formation, which was accompanied by augmented ASM-ceramide-MR redox signaling and NLRP3 inflammasome formation and activation in the arterial endothelium." (PMID 36252682, 2022). "Li and colleagues recently found that acid sphingomyelinase (ASMase, encoded by gene Smpd1) and ceramide-associated membrane raft (MR) signaling platforms were involved in endothelial NLRP3 inflammasome activation and atherogenesis resulting from hypercholesterolemia." (PMID 32226786, 2020). "Together, these data suggest that EC-specific Smpd1 gene overexpression enhances endothelial NLRP3 inflammasome formation and activation in the carotid arteries of mice during hypercholesterolemia." (PMID 36252682, 2022).
liver cancer (3 papers, 2023 to 2025). An epithelial or non-epithelial malignant neoplasm that arises from the liver. "Reduced mRNA levels of SMPD1, the gene encoding for ASMase, is found in several types of cancer, including liver cancer, renal cancer and head and neck carcinomas." (PMID 38474423, 2024).
Fabry disease (2 papers, 2021 to 2022). Fabry disease (FD) is a progressive, inherited, multisystemic lysosomal storage disease characterized by specific neurological, cutaneous, renal, cardiovascular, cochleo-vestibular and cerebrovascular manifestations. "TRPML1 signaling or TRPML1‐mediated Ca2+ release is similarly impaired in other LSDs such as Niemann–Pick type C1 (NPC1), Niemann–Pick type A (NPA; also called infantile neurovisceral form of acid sphingomyelinase (SMPD1) deficiency), and Fabry disease." (PMID 35929194, 2022).
GM1 gangliosidosis (2 papers, 2019 to 2020). A rare lysosomal storage disorder characterized biochemically by deficient beta-galactosidase activity and clinically by a wide range of variable neurovisceral, ophthalmological and dysmorphic features. "Furthermore, we detected that three other patients, an infant with GM1 gangliosidosis, an infant with MPS 3A, and an adult with type 2 elliptocytosis, were also carriers of confirmed pathogenic mutations in the SMPD1, SLC17A5, and HEXB genes, respectively." (PMID 32071839, 2020).
liver disease (2 papers, 2017 to 2020). "In a series of 13 Chilean pediatric patients homozygous for the SMPD1 p.(Ala359Asp) (A359D) mutation associated with moderate to severe NPD B, five (38.5%) patients developed clinically relevant liver disease due to progressive cirrhosis." (PMID 28228103, 2017).
Lysosomal disease (2 papers, 2021 to 2022). "Acid SMase (ASMase or SMPD1) is an enzyme found in lysosomes, and its deficiency leads to an inherited lysosomal disease." (PMID 35565311, 2022).
myocardial ischemia (2 papers, 2020 to 2022). A disorder of cardiac function caused by insufficient blood flow to the muscle tissue of the heart. "The abnormal accumulation of ceramides due to the mutation of SMPD1 plays an essential role in acute myocardial ischemia." (PMID 36292100, 2022). "In a mouse model of myocardial ischemia/ reperfusion, heterozygous Smpd1 deficiency did not reduce cardiac injury or improve heart function." (PMID 33057972, 2020).
non-alcoholic steatohepatitis (2 papers, 2017 to 2020). "Altered SMPD1 activity has been linked to the pathogenesis of numerous disease entities such as alcoholic cirrhosis, non-alcoholic steatohepatitis, as well as cachexia and mortality in chronic heart failure." (PMID 28955042, 2017).
retinal degeneration (2 papers, 2015 to 2020). Degeneration of the retina. "In retinal I/R, heterozygous Smpd1 deficiency protected against retinal degeneration." (PMID 33057972, 2020).
synucleinopathies (2 papers, 2017 to 2024). "Polymorphisms in genes encoding lysosomal enzymes, acid sphingomyelinase (SMPD1 gene), and β-glucocerebrosidase (GBA, GBA1 gene), are also risk factors for synucleinopathies." (PMID 29021741, 2017).
brain infarcts (1 paper, 2020). "In line with the exacerbated brain infarcts, the density of DNA-fragmented, that is, irreversibly injured, TUNEL + cells was significantly increased in the reperfused ischemic striatum of Smpd1−/− compared with Smpd1+/+ mice." (PMID 33057972, 2020). "In this study, PMN depletion by delivery of anti-Ly6G antibody did not reduce I/R injury in Smpd1+/+ mice, which exhibited localized striatal brain infarcts." (PMID 33057972, 2020).
Cognitive impairment (1 paper, 2022). Abnormal cognition is characterized by deficits in thinking, reasoning, or remembering. "miR-induced Smpd1 knockdown and tamoxifen-induced endothelial-specific Smpd1 knockout reduced blood–brain barrier disturbance, neuronal degeneration in cortex and hippocampus and cognitive impairment in aged mice." (PMID 36038749, 2022).
developmental delay (1 paper, 2024). "The exclusion criteria for pediatric patients aged <3 years included a clinical diagnosis of infantile-onset ASMD (NPD A) with evidence of developmental delay, or homozygosity for specific SMPD1 gene mutations (R496l, L302P, P330fs*52 or any combination of these mutations)." (PMID 39834487, 2024).
endometriosis (1 paper, 2022). The growth of functional endometrial tissue in anatomic sites outside the uterine body. "Gene expression involved in ceramide synthesis (CERS1, SPTL1, and SMPD1) and autophagy (BECN1, LAMP, and PC3) were significantly higher in CCs with endometriosis according to FASN, BECN1, and LAMP protein expressions." (PMID 35992117, 2022).
Ewing sarcoma (1 paper, 2025). A small round cell tumor that lacks morphologic, immunohistochemical, and electron microscopic evidence of neuroectodermal differentiation. "For example, SMPD1 and GPR64 are downstream targets of EWS-FLI1, and the SMPD1–ceramide–GPR64 axis promotes Ewing’s sarcoma growth." (PMID 40977697, 2025).
ichthyosis (1 paper, 2019). Disorders of cornification that are characterized by visible scaling and/or hyperkeratosis of most or all of the skin. "In line with this, the expression of SPTLC2 and SMPD1 and seven ichthyosis‐causing genes involved in the pathway of acylCer and CLE formation was induced in the range of 2‐4 times." (PMID 30372788, 2019).
infiltrating ductal carcinoma (1 paper, 2021). "A non-metastatic infiltrating ductal carcinoma was diagnosed in a 41.2 year old former smoker female patient (60 pack-years) with the SMPD1 genotype p.Q134X/p.G244R." (PMID 34768550, 2021).
intrauterine growth restriction (1 paper, 2025). "We demonstrate that acid sphingomyelinase (Smpd1) is required for normal placental development in mouse, and its deficiency results in an intrauterine growth restriction phenotype." (PMID 40888736, 2025).
neuroendocrine small-cell lung carcinoma (1 paper, 2021). "A metastatic neuroendocrine small-cell lung carcinoma was diagnosed in a 58.2 year old former smoker male patient (30 pack-years) with the SMPD1 genotype p.R610del/p.R610del." (PMID 34768550, 2021).
papillary thyroid carcinoma (1 paper, 2021). "A papillary thyroid carcinoma (pT1bm N0 R0 V0 according to current classification) was diagnosed in a 40.3 year old former smoker male patient (15 pack-years) with the SMPD1 genotype p.G247S/p.R476W." (PMID 34768550, 2021).
pulmonary disease (1 paper, 2025). "Patient 1, a 59-year-old man with a homozygous SMPD1 mutation (c.[Arg610del]), showed advanced pulmonary disease and liver steatosis." (PMID 41211123, 2025).
Segawa syndrome (1 paper, 2024). "Second, when NPB and Segawa syndrome are highly suspected, screening for tyrosine hydroxylase (TH) and sphingomyelin phosphodiesterase-1 (SMPD1) gene mutations is critical to determine an accurate diagnosis." (PMID 38826802, 2024).
skin cancer (1 paper, 2022). "In contrast to CERS6, there was more SMPD1 mRNA, which encodes ceramide-generating acid sphingomyelinase, in skin cancer tissue than in nontumor tissue." (PMID 36077841, 2022).
squamous cell carcinoma (1 paper, 2021). A carcinoma arising from squamous epithelial cells. "A typical and metastatic well-differentiated squamous cell carcinoma was diagnosed in a 57.7 year old smoker male patient (5 pack-years) with the SMPD1 genotype p.R610del/p.R610del." (PMID 34768550, 2021).
urothelial carcinoma of the bladder (1 paper, 2021). "A non-metastatic high-grade urothelial carcinoma of the bladder was diagnosed in a 52.3 year old former smoker male patient (50 pack-years) with the SMPD1 genotype p.R610del/p.R610del." (PMID 34768550, 2021).